CAT (catalase)
Diseases named in the same sentence as CAT in open-access papers (continued):
Sharing a sentence is not in itself a finding about the gene and the disease.
autism (13 papers, 2012 to 2025). Persistent deficits in social interaction and communication and interaction as well as a markedly restricted repertoire of activity and interest as well as repetitive patterns of behavior. "This imbalance directly correlates with oxidative stress, as seen in the elevated levels of lipid peroxidation and decreased antioxidant defenses (GSH, catalase), which have been previously implicated in autism-related neuroinflammation and neurodegeneration." (PMID 40171233, 2025). "Other studies showed the reduction of the total GSH levels and altered GPx, SOD, and CAT activities in patients with autism compared to the controls." (PMID 33335642, 2020). "In summary, in the groups exhibiting autistic features, there was a notable rise in brain MDA levels, alongside a significant reduction in GSH and CAT levels compared to the SH (healthy) groups, suggesting that the experimental autism model triggered oxidative stress." (PMID 39910830, 2025). "A recent report has indicated that developmental exposure to PM2.5 caused autism-like behaviors, such as poor social interaction and repetitive behavior, accompanied by lower oxytocin receptor (OXTR) protein level, catalase activity, and glutathione (GSH) concentration, in 7-week-old male rats." (PMID 33430368, 2021). "Behavioral tests were conducted wherein oxidative stress markers (such as lipid peroxidation, advanced protein oxidation product, NO, and GSH) and the activity of SOD and CAT were estimated to confirm the mouse model of autism and assess the effect of astaxanthin." (PMID 26437420, 2015). "MDA level was significantly increased, and GSH, catalase (CAT), and SOD levels were significantly reduced in the autism-induced group when compared to the control group." (PMID 38344592, 2024). "The results of this study are also in line with earlier research, which found that the autism-induced group's hippocampal GSH, CAT, and SOD levels were decreased and their MDA levels were raised, indicating lipid peroxidation." (PMID 38344592, 2024). "Additionally, APZ successfully mitigated oxidative stress in rats with autism by normalizing the GSH and catalase levels while simultaneously reducing MDA in the targeted brain regions investigated." (PMID 38256307, 2023). "The findings of the present study revealed a significant increase in MD, a significant marker of oxidative stress, with a concomitant decrease of catalase, GSH and GPX in the brain homogenates of the PA-treated rats, which corroborated the role of oxidative stress in the etiology of autism." (PMID 22531301, 2012).
brain infarction (13 papers, 2013 to 2025). Tissue necrosis in any area of the brain, including the cerebral hemispheres, the cerebellum, and the brain stem. "Serum levels of RBP4 and 8-iso-PGF2α were significantly higher, whereas serum level of CAT was significantly lower in patients with cerebral infarction compared with controls (P < 0.01)." (PMID 36304097, 2022). "This study found that the serum level of RBP4 not only positively correlated with carotid artery IMT and atherosclerotic plaque area but also significantly positively correlated with the serum level of 8-iso-PGF2α and negatively correlated with CAT level in elderly patients with cerebral infarction." (PMID 36304097, 2022). "Next, rats were killed, andbrains were isolated for measuring brain infarction volume, blood-brain barrier (BBB) permeability, edema, the activityof superoxide dismutase (SOD), and catalase (CAT) and also, the level of malondialdehyde (MDA)." (PMID 34308573, 2021). "After 24 h reperfusion, cerebral infarction and superoxide dismutase (SOD) and catalase activities, as well as malondialdehyde (MDA), glutathione, and NOx contents were determined in the right hemispheres." (PMID 30957616, 2019). "The determinations of neurological score and temperature sensation were performed every 7 days throughout the study period, while the determinations of brain infarction volume, MDA level, and the activities of SOD, CAT, and GSH-Px were performed 24 hr after Rt.MCAO." (PMID 24367723, 2013). "Glycyrrhizin reduces cerebral infarction volume and attenuates CI/RI by lowering MDA levels, decreasing the number of positive apoptotic cells, and up‐regulating SOD, catalase, and GSH‐PX activities, indicating that glycyrrhizin may be a potential anti‐ischemic drug." (PMID 40566933, 2025).
Cirrhosis (13 papers, 2012 to 2025). A chronic disorder of the liver in which liver tissue becomes scarred and is partially replaced by regenerative nodules and fibrotic tissue resulting in loss of liver function. "The oxidative tissue damage in cirrhosis causes a significantly low level of catalase." (PMID 25254057, 2014). "Collagen I, α-smooth muscle actin (α-SMA), HIF-1α, and CAT expression of normal and cirrhosis tissues were then subjected to immunofluorescence staining." (PMID 36797395, 2023). "In this work, we examined the hypoxia and decreased CAT in clinical specimens from cirrhosis patients." (PMID 36797395, 2023). "Clinical specimens of cirrhosis patients and liver fibrotic mice are collected in this work, and results show that CAT decrease is closely correlated with hypoxia-induced transforminmg growth factor β1 (TGF-β1)." (PMID 36797395, 2023). "ROS affects the antioxidant defense mechanisms, decreases the activity of SOD, CAT, and GPX that causes liver injury, cirrhosis development, and hepatocarcinoma." (PMID 22649471, 2012). "This decrease in CAT activity in hepatic cirrhosis patients may be due to the inactivation of catalase by H2O2." (PMID 34616224, 2021). "CCl4 induced hepatic-cirrhosis in rat resulted in decrease of antioxidant enzyme activities such as catalase, peroxidase, superoxide dismutase, glutathione peroxidase, glutathione-S-transferase and glutathione reductase-which were restored towards the normal level with ANM." (PMID 27488054, 2016). "This may explain the decreased catalase activity in the sera of hepatic cirrhosis patients." (PMID 34616224, 2021). "In a study conducted in cirrhosis patients, MDA activity was found below the lower decision line, while SOD, CAT and GSH activity were found above the upper decision line." (PMID 35720997, 2022). "In cirrhosis patients, MDA and GSH activities were between the decision lines, and SOD and CAT activities were above the upper decision line." (PMID 35720997, 2022). "The aim of this study was to determine the levels of lipid peroxidation (MDA) and antioxidants such as reduced glutathione (GSH), catalase (CAT) and superoxide dismutase (SOD) in the blood serum of patients with cirrhosis and liver transplantation." (PMID 34616224, 2021). "This the first study demonstrating the roles of MDA, SOD, CAT, and GSH in hepatic cirrhosis and liver transplantation." (PMID 34616224, 2021). "Other studies show that patients with cirrhosis present increased levels of pro-oxidant markers, e.g., serum MDA and reduced levels of antioxidant factors, e.g., catalase, SOD, and reduced blood GSH, indicating that oxidative stress is known to factor into cirrhosis development." (PMID 38003721, 2023). "In addition, the treatment of low-dose or high-dose vitamin D effectively inhibited oxidative stress by increasing CAT, GSH-Px, and SOD and attenuating MDA levels compared with the cirrhosis model group." (PMID 37273916, 2023). "This study is the first one to show how MDA, SOD, CAT and GSH levels change in liver cirrhosis and liver transplantation, while further studies are essential to investigate antioxidant enzymes and oxidative stress status in patients with cirrhosis and liver transplantation." (PMID 34616224, 2021). "Levels of catalase (CAT), SOD, GSH, and MDA, which are biomarkers related to oxidative stress and the antioxidant defense system, were examined in HCC patients with and without cirrhosis and infected with HCV." (PMID 41393733, 2025).
Crohn disease (13 papers, 2017 to 2025). A gastrointestinal disorder characterized by chronic inflammation involving all layers of the intestinal wall, noncaseating granulomas affecting the intestinal wall and regional lymph nodes, and transmural fibrosis. "Treatment of Crohn’s disease mice with CAT or SOD producing Lactobacillus casei strain BL23 showed faster recovery of initial weight loss, increased enzymatic activities in the intestine, and less extent of intestinal inflammation compared to mice that did not receive bacterial supplementation." (PMID 38791478, 2024). "Interestingly, genetically modified Lactobacilli strains synthetizing SOD/catalase showed capability to relieve symptoms of a mouse model of Crohn’s disease vs. “wild-type” strains." (PMID 35010297, 2021). "Anti-inflammatory effects of CAT or SOD-producing Lactobacillus casei strain BL23 have been reported using a murine model of 2,4,6-trinitrobenzene sulfonic acid (TNBS)-induced Crohn’s disease." (PMID 38791478, 2024). "•MDA, PON-1, CAT, albumin, transferrin, and TAC indicate Crohn's disease flares." (PMID 39368456, 2024).
endometriosis (13 papers, 2006 to 2025). The growth of functional endometrial tissue in anatomic sites outside the uterine body. "Authors suggest that the implication of GPX1 and CAT gene polymorphisms can cause endometriosis but request more extensive studies to confirm their findings." (PMID 36013572, 2022). "Very few articles address the association between aberrant expression of GPX1 and CAT genes and endometriosis." (PMID 36013572, 2022). "Polymorphism of GPX1 198Pro > Leu and CAT-262C > T are both associated with symptomatic endometriosis, and CAT-262C > T and GSTM1 are risk factors for disease’s development." (PMID 36013572, 2022). "According to our results, CAT-262C > T is a risk factor for endometriosis development." (PMID 36013572, 2022). "While in normal cells various antioxidants dispose of ROS from the system, insufficient levels of SOD and catalase in endometriosis are indicative of inefficient scavenging effect leading to a continued prevalence of ROS in the system." (PMID 23984345, 2013). "In patients with endometriosis and adenomyosis, SOD and CAT were found to be abnormally expressed, while patients with endometriosis have lowered GPx activity." (PMID 20030853, 2009). "Abnormal expression of catalase in the eutopic and ectopic endometrium strongly suggests pathologic involvement of free radicals in endometriosis and adenomyosis." (PMID 16893473, 2006). "Effective inhibitors of ROS related to endometriosis are vitamins C and E, astaxanthin, fatty acid-binding protein 4, cerium oxide nanoparticles (nanoceria), osteopontin, sphingosine 1-phosphate, N-acetyl-L-cysteine, catalase, and a high-antioxidant diet." (PMID 40722981, 2025). "In endometriosis, an increase in SOD activity and a decrease in CAT activity have been reported, which leads to increased production of reactive oxygen species (ROS), promoting the proliferative phenotype." (PMID 38785987, 2024). "From the present study, OS condition is indicated in endometriosis, as evidenced by lower expression of TAC, SOD, GSH, catalase, and higher ROS generation." (PMID 23984345, 2013). "ROS, LPO, and AOPP were observed to be increased significantly whereas TAC, SOD, catalase, and GSH levels were significantly less in endometriosis women as compared to controls." (PMID 23984345, 2013). "The catalase (CAT) relative gene expression showed a tendency of substantial and significant decrease (P = 0.003) in the endometriosis group (0.033 ± 0.009) whereas only slightly decreased in the endometrial cancer samples (0.145 ± 0.021) compared with the healthy controls (0.225 ± 0.044)." (PMID 37968795, 2024). "This is the first study investigating the association of CAT-262C > T, GPX1 198Pro > Leu, GSTT1, and GSTM1 gene polymorphisms in the Eastern European women population with and without endometriosis, having analyzed a large number of patients." (PMID 36013572, 2022).
osteoarthritis (12 papers, 2013 to 2024). A noninflammatory degenerative joint disease occurring chiefly in older persons, characterized by degeneration of the articular cartilage, hypertrophy of bone at the margins and changes in the synovial membrane. "In summary, CAT, a metabolite of gut microbiota, is a potential drug for the treatment of ferroptosis‐relative osteoarthritis and the association between the ‘gut‐joint’ axis may provide a new strategy for the treatment of aging diseases." (PMID 36890785, 2023). "To our knowledge, we are the first to report that the protective effect of CAT against osteoarthritis is mediated by the inhibition of HIF‐1 α and activation of SLC2A1, thereby inhibiting ferroptosis progression." (PMID 36890785, 2023). "According to the findings, CAT ameliorates the progression of osteoarthritis and inhibits the level of mitochondrial autophagy." (PMID 36890785, 2023). "Several works demonstrate the decrease in GSH level, GPx activity and CAT levels in both patients and osteoarthritic rats, confirming the role of oxidative stress in osteoarthritis pathogenesis." (PMID 32532064, 2020). "Altindag and colleagues showed lower serum catalase activity and thiol levels in osteoarthritis patients, compared to controls." (PMID 32532064, 2020). "It should be noted that in patients with osteoarthritis, the J haplogroup population did have higher levels of catalase, an antioxidant enzyme involved in the removal of hydrogen peroxide." (PMID 23365660, 2013). "In addition, we further investigated the possibile mechanism of HIF‐1a expression and SLC2A1 which effect by gut microbiota metabolite CAT and provide a theoretical basis for CAT treatment of osteoarthritis." (PMID 36890785, 2023). "Finally, to clarify the effect of SLC2A1 on the onset and progression of osteoarthritis treatment with CAT, 8‐week‐old mice were injected intra‐articularly with AVV‐specific expression of SLC2A1‐specific shRNA." (PMID 36890785, 2023). "The negative correlation between OARSI score and CAT was investigated which may provide that CAT, a gut microbiota metabolite, is a potentially reliable drug for the treatment of osteoarthritis." (PMID 36890785, 2023). "Therefore, this study aimed to investigate changes in gut microbiota and metabolites in osteoarthritis and found the role of CAT in osteoarthritis which prevents ferroptosis." (PMID 36890785, 2023). "The role and mechanism of CAT in osteoarthritis are unknown." (PMID 36890785, 2023). "However, the protective effect of CAT against ferroptosis‐dependent osteoarthritis could be eliminated by silencing SLC2A1." (PMID 36890785, 2023). "Moreover, CAT reduced ferroptosis‐dependent osteoarthritis in vivo and in vitro." (PMID 36890785, 2023). "In a study conducted on rats with osteoarthritis, JHF supplementation enhanced SOD, CAT, and GSH-Px production in a dose-dependent manner while significantly decreasing the amount of MDA, similar to our findings." (PMID 38665778, 2024). "Our findings indicated that CAT inhibited HIF‐1a expression and reduced ferroptosis‐relative osteoarthritis progression by activating SLC2A1." (PMID 36890785, 2023). "Our findings indicated that CAT inhibited HIF‐1a expression and reduced ferroptosis‐dependent osteoarthritis progression by activating SLC2A1." (PMID 36890785, 2023). "Rats with osteoarthritis had greater MDA but lower SOD, CAT, and GPx activities compared with those of rats in the control group (p < 0.05)." (PMID 34282229, 2021). "Also, we found that CAT inhibited HIF‐1a expression and reduced ferroptosis‐dependent osteoarthritis progression by activating SLC2A1." (PMID 36890785, 2023). "Finally, compared with catalase (CAT), Ta-NH2 NPs exhibited long-term therapeutic effect in monosodium iodoacetate (MIA) induced osteoarthritis model." (PMID 36714006, 2023).
osteoarthritis (continued). "Although other literature studies concerning NR showed an improvement in CAT levels in cell cultures and animal models, to our knowledge, there are no current records concerning CAT in osteoarthritis." (PMID 37959383, 2023). "Fullerene-like MoS2 (F-MoS2) is another interesting TMDC-NZs with CAT-/SOD-like activities under physiological settings that appropriate it for using for the non-surgical treatment of osteoarthritis." (PMID 35009484, 2022). "However, the role and mechanism of CAT in osteoarthritis are not clear." (PMID 36890785, 2023).
bipolar disorder (11 papers, 2015 to 2025). A disorder of the brain that causes unusual shifts in mood, energy, activity levels and the ability to carry out day-to-day tasks. "Data have been reported for lower SOD and CAT levels in patients with bipolar disorder than in a healthy control group." (PMID 39473913, 2024). "In another study, it was found that there was an imbalance in antioxidant enzymes in bipolar depression, CAT and GPx increased, and the SOD/CAT ratio decreased, and a reactive increase in antioxidant enzyme levels was shown in the same patient group with the treatment of bipolar disorder." (PMID 39473913, 2024). "In bipolar disorder, the activities of superoxide dismutases (SODs) and catalase (CAT) have been found to be decreased in the blood, while the activity of glutathione peroxidases (GPXs) has been shown to be comparable between bipolar patients and healthy individuals." (PMID 33644051, 2021). "There is consistent evidence from peripheral marker studies that the brain’s primary antioxidants, GSH, catalase (CAT), superoxide dismutase (SOD), and GSH peroxidase are altered in those with bipolar disorder." (PMID 25889215, 2015). "However, research conducted by Loo JL indicates a statistically significant elevation in CAT concentration in the blood plasma of patients expressing suicidal thoughts compared to patients diagnosed with bipolar disorder without suicidal thoughts and to the healthy control group." (PMID 38721610, 2024).
brain injury (11 papers, 2017 to 2025). Acute and chronic (see also brain INJURIES, CHRONIC) injuries to the brain, including the cerebral hemispheres, CEREBELLUM, and brain STEM. "In a study fecal microbiota transplantation elevated SOD and CAT activities and GSH/GSSG ratio and diminished ROS, GSSG, and MDA levels in the hippocampus after traumatic brain injury." (PMID 36620458, 2022). "Using DS-catalase complexes, we developed catalase-loaded PLGA-PEG nanoparticles and evaluated their efficacy in the Vannucci model of unilateral hypoxic-ischemic brain injury in postnatal day 10 rats." (PMID 34452092, 2021). "In contrast, the mechanism of single-atom Pt/CeO2 for the brain trauma treatment was to scavenge RONS, exhibiting multienzyme activities such as peroxidase (POD)-like, catalase (CAT)-like, and oxide (OXD)-like catalytic activities." (PMID 33333964, 2020). "Rhein played a similar effect to Rhubarb in the treatment of traumatic brain injury through antioxidation (via boosting the SOD, CAT activities, GSH level, and GSH/GSSG ratio and concomitantly diminishing MDA and GSSG levels)." (PMID 28264680, 2017).